TLE4 (TLE family member 4, transcriptional corepressor)
Description:
Transcriptional corepressor that binds to a number of transcription factors. Inhibits the transcriptional activation mediated by PAX5, and by CTNNB1 and TCF family members in Wnt signaling. The effects of full-length TLE family members may be modulated by association with dominant-negative AES. Essential for the transcriptional repressor activity of SIX3 during retina and lens development and for SIX3 transcriptional auto-repression (By similarity). Involved in transcriptional repression of GNRHR and enhances MSX1-mediated transcriptional repression of CGA/alpha-GSU (By similarity).
Synonyms: GRG4; E(spl); ESG; BCE-1; BCE1; E(spI); ESG4; Grg-4
Tractability: PROTAC: UniProt records ubiquitination sites on it; ubiquitination databases record sites on it; its protein half-life has been measured.
Gene: Protein-coding gene on chromosome 9 (79,571,773 to 79,726,882, forward strand). Ensembl gene ENSG00000106829.
Subcellular location: Nucleus
Subcellular location (Human Protein Atlas): Nucleoplasm; Mitochondria
Pathways (Reactome):
Signal Transduction: Deactivation of the beta-catenin transactivating complex; Formation of the beta-catenin:TCF transactivating complex; NOTCH1 Intracellular Domain Regulates Transcription; Repression of WNT target genes
Gene Ontology:
Molecular function: protein binding; transcription corepressor activity; chromatin binding; DNA-binding transcription factor binding
Biological process: negative regulation of canonical Wnt signaling pathway; negative regulation of transcription by RNA polymerase II; regulation of DNA-templated transcription
Cellular component: beta-catenin-TCF complex; nucleoplasm; nucleus; transcription regulator complex
Genetic constraint (gnomAD): Loss-of-function variants: 8 observed, 86.83 expected, observed/expected ratio (o/e) 0.0921, 90% interval 0.053 to 0.17. The upper end of that interval is the gene's LOEUF score, 0.17, which puts it in group 1 of 6, group 1 being the genes least tolerant of losing a copy. Missense variants: 631 observed, 980.87 expected, observed/expected ratio (o/e) 0.64, 90% interval 0.6 to 0.69. Synonymous variants: 350 observed, 374.29 expected, observed/expected ratio (o/e) 0.94, 90% interval 0.86 to 1.02.
Homologues: Orthologues: chimpanzee TLE4 (99% identical), macaque TLE4 (99% identical), mouse Tle4 (99% identical), rat Tle4 (99% identical), pig TLE4 (99% identical), dog TLE4 (99% identical), tropical clawed frog tle4 (98% identical), guinea pig TLE4 (98% identical), rabbit TLE4 (92% identical). Paralogues in human: TLE1 (86% identical), TLE3 (82% identical), TLE2 (67% identical), TLE6 (20% identical), TLE7 (19% identical), TLE5 (17% identical).
Diseases named in the same sentence as TLE4 in open-access papers:
TLE4 is named in the same sentence as 40 diseases in open-access papers, as found by Europe PMC text mining. Sharing a sentence is not in itself a finding about the gene and the disease. The quoted sentences say what the papers report.
asthma (7 papers, 2009 to 2021). "For example, TLE4 was previously associated with asthma in a GWAS with the associated SNP lying upstream of the gene likely affecting its regulation." (PMID 29329322, 2018). "We implicated several polymorphisms in or near TLE4 on chromosome 9q21.31 (a novel candidate region for childhood asthma) and replicated one polymorphism in an independent study of childhood-onset asthmatics with atopy and their parents of Mexican ethnicity." (PMID 19714205, 2009). "An alteration of B-cell differentiation involving TLE4 could be relevant to immune development and thus asthma." (PMID 19714205, 2009). "Association results from additive modeling for SNPs in the region spanning TLE4 and its upstream region (chromosome 9 nucleotide positions from 81,114,500 to 81,531,500, NCBI build 36.3) were obtained from the previous GWASs of asthma." (PMID 19714205, 2009).
colorectal cancer (5 papers, 2016 to 2025). A primary or metastatic malignant neoplasm that affects the colon or rectum. "TLE4 in colorectal cancer (CRC) tissues were significantly higher than that in their matched adjacent intestine epithelial tissues." (PMID 35057823, 2022). "Increased RHOU expression was detected in the EGFR PC9-CR cells, while the well-known oncogene in lung and colorectal cancer TLE4 was also induced by cisplatin in the PC9-CR cells." (PMID 34065402, 2021). "In this study, we found that the expression of TLE4 in colorectal cancer (CRC) tissues was significantly higher than that in their matched adjacent intestine epithelial tissues." (PMID 26701208, 2016). "TLE4 promote colorectal cancer progression through activation of the signalling pathway." (PMID 35057823, 2022). "The results from this study demonstrated that TLE4 can activate c-Jun and JNK in colorectal cancer cells, and followed by alteration of their downstream targets cyclinD1 and P27Kip1." (PMID 26701208, 2016).
acute myeloid leukemia (3 papers, 2014 to 2025). Acute myeloid leukemia (AML) is a group of neoplasms arising from precursor cells committed to the myeloid cell-line differentiation. "For instance, TLE4 is underexpressed in acute myeloid leukemia, where it acts as a tumor suppressor." (PMID 40406521, 2025). "TLE4 belongs to a highly conserved transcriptional co-repressor family and was believed to be a tumor suppressor gene in acute myeloid leukemia." (PMID 26701208, 2016). "The Groucho transcriptional co-repressor TLE4 protein has been shown to be a tumor suppressor in a subset of acute myeloid leukemia." (PMID 26701208, 2016). "Tle4, a transcriptional corepressor, acts as a tumor suppressor gene in a subset of acute myeloid leukemia, yet little is known about its function in normal and malignant hematopoiesis or in mammalian development." (PMID 25153823, 2014). "Both of TLE1 and TLE4 localize in chromosome 9q, the commonly deleted region in acute myeloid leukemia (AML)." (PMID 26701208, 2016). "In addition, TLE4 acts as a tumor suppressor gene in acute myeloid leukemia." (PMID 26701208, 2016).
leukemia (3 papers, 2013 to 2024). A malignant (clonal) hematologic disorder, involving hematopoietic stem cells and characterized by the presence of primitive or atypical myeloid or lymphoid cells in the bone marrow and the blood. "Some were already associated with T-CD8+ leukemias (Il2ra; and Pdgfrb) and others were associated with other types of T-leukemias or cancer (Irf4, Hrb, Depdc6, Als2cl, Tle4 and Cdc42ep3), thus validating our approach." (PMID 23902727, 2013). "Besides, some of the DMRs with the strongest increases were adjacent to genes such as CEBPA, LEF1, PLK2, MEIS1 or TLE4, which have a known involvement in either leukemia or hematopoiesis." (PMID 38972954, 2024). "Moreover, our observations provide further insight and affirmation to previous findings that implicate Tle4 as a critical regulator of leukemia and other states of hematological dysregulation." (PMID 25153823, 2014).
B cell lymphopenia (2 papers, 2014 to 2016). "Tle4 knockout mice exhibit leukocytopenia, B cell lymphopenia, and significant reductions in haematopoietic stem and progenitor cells." (PMID 27434032, 2016). "By two weeks of age, Tle4 knockout mice exhibit leukocytopenia, B cell lymphopenia, and significant reductions in hematopoietic stem and progenitor cells." (PMID 25153823, 2014). "In summary, deletion of Tle4 resulted in B-cell lymphopenia in peripheral blood and decreased cellularity in hematopoietic organs." (PMID 25153823, 2014).
childhood asthma (2 papers, 2009 to 2011). "This region contains a biologically plausible novel susceptibility gene for childhood asthma, TLE4, but further work is needed to decipher whether TLE4 or a nearby gene explain the signals from the chromosome 9q21.31 region." (PMID 19714205, 2009).
glioblastoma (2 papers, 2024). The most malignant astrocytic tumor (WHO grade IV). "Whole-genome CRISPR/Cas9 screening was performed in CAR-T cells and co-cultured with Glioblastoma (GBM) stem cells (GSCs) to explore the PD-1 dependence genes such as TLE4 and IKZF2 for cancer treatment." (PMID 38816739, 2024).
Miscarriage (2 papers, 2020 to 2022). A pregnancy that ends at a stage in which the fetus is incapable of surviving on its own, defined as the spontaneous loss of a fetus before the 22th week of pregnancy. "Among the prioritized genes we found STAG2 coding for the cohesin complex subunit, for which inactivation in mouse is lethal, and TLE4 a target of Notch and Wnt, physically interacting with a region on chromosome 9 associated to miscarriages." (PMID 35132093, 2022). "Mapping of potential candidate genes at associated loci identified several genes (FGF9, TLE1, TLE4, E2F8, SIK1) with a plausible biological role in placental biology and miscarriage etiopathogenesis." (PMID 33239672, 2020).
myeloid leukemia (2 papers, 2021 to 2023). A clonal proliferation of myeloid cells and their precursors in the bone marrow, peripheral blood, and spleen. "Only one has study revealed that forced Tle4 expression caused apoptosis and cell death in myeloid leukemia, which is consistent with our current findings that Tle4 knockdown attenuated I/R-induced apoptosis of RGCs." (PMID 36653745, 2023). "Having identified the tumor suppressor role of TLE4 in myeloid leukemias, we generated a novel Tle4 knockout mouse model to better understand its role in mammalian development." (PMID 34422801, 2021).
autism (1 paper, 2015). Persistent deficits in social interaction and communication and interaction as well as a markedly restricted repertoire of activity and interest as well as repetitive patterns of behavior. "To examine the protein level of the RNAseq results in mouse CAD cells, we tested genes involved in autism risk (NLGN1), neurodegeneration (ATXN1), neurogenesis (REST), embryonic development (TLE4), and neuronal migration (KIF1A)." (PMID 26094033, 2015).
autism spectrum disorder (1 paper, 2022). A spectrum of developmental disorders that includes autism, and Asperger syndrome. "We also found a specific enrichment of autism spectrum disorder risk in a deep-layer thalamic-projecting neuronal population L6 TLE4." (PMID 35419551, 2022). "In particular, the enrichment of autism spectrum disorder genetic risk in L4 PLCH1 and L6 TLE4 cells can only be identified in vestigial enhancers." (PMID 35419551, 2022).
colon cancer (1 paper, 2022). "In colon cancer, HDAC3 knockdown can suppress β-catenin translocation from the plasma membrane to the nucleus and increase the expression of Wnt inhibitors TLE1, TLE4 and SMO." (PMID 34991620, 2022).
Diabetic Nephropathy (1 paper, 2021). "Immunofluorescence labeling of glomeruli with GLEPP1 as a glomerular marker and TLE4 as a podocyte nuclear marker revealed a decrease in podocyte density in all grades of Diabetic Nephropathy cases relative to healthy control tissue." (PMID 34335284, 2021).
ischemia (1 paper, 2023). A hypoperfusion of the BLOOD through an organ or tissue caused by a PATHOLOGIC CONSTRICTION or obstruction of its BLOOD VESSELS, or an absence of BLOOD CIRCULATION. "Given that Tle4 is a potential target gene for miR-155-5p, we further investigated the role of Tle4 in ischemia-induced RGCs apoptosis." (PMID 36653745, 2023). "Mechanistically, the results demonstrated that lncRNA uc007nnj. acts as ceRNA competitively binding miR-155-5p, thereby enhancing the expression levels of Tle4, thus aggravating ischemia-related apoptosis in RGCs." (PMID 36653745, 2023).
lymph node metastasis (1 paper, 2016). "The results exhibited that the high expression level of TLE4 significantly was associated with poor Dukes stage (P = 0.001) and more lymph node metastasis (P = 0.001)." (PMID 26701208, 2016). "Cox regression analyses revealed that lymph node metastasis and TLE4 expression were recognized as independent prognostic factors in this study." (PMID 26701208, 2016). "Spearman correlation analysis was further used to confirm these data, and the coefficients for the correlations between TLE4 expression and Dukes stage and lymph node metastasis were 0.506 (P < 0.001) and 0.421 (P < 0.001), respectively." (PMID 26701208, 2016). "In addition, high expression of TLE4 was significantly correlated with advanced Dukes stage, lymph node metastasis and poor prognosis of CRC." (PMID 26701208, 2016).
lymphoma (1 paper, 2022). A malignant (clonal) proliferation of B- lymphocytes or T- lymphocytes which involves the lymph nodes, bone marrow and/or extranodal sites. "In addition, overexpression of TLE1 or TLE4 inhibited the in vitro proliferation of lymphoma cells harboring AML1-ETO, and knocking down a TLE homolog promoted the growth of lymphoma in a zebrafish model." (PMID 36438567, 2022).
melanoma (1 paper, 2024). A malignant, usually aggressive tumor composed of atypical, neoplastic melanocytes. "Other genes involved in oncogenesis bore melanoma-specific ZEB1 binding sites which were either lost in MDA-MB-231 cells, such as for the WNT regulators TLE4 (Groucho) SFRP1 or FOXC2." (PMID 38519642, 2024).
Obesity (1 paper, 2023). Accumulation of substantial excess body fat. "TLE4 remains interesting as a transcriptional corepressor, as it has been linked to obesity in both mice and humans before." (PMID 36980854, 2023).
periodontitis (1 paper, 2025). An acute or chronic inflammatory process that affects the tissues that surround and support the teeth. "After integrating DNA methylation with transcriptome profiles, GRASP, HLA-DMB, HLA-DMA, CAB39, NCOA2 and TLE4 were identified as candidate genes in periodontitis PMNs." (PMID 40267082, 2025). "Our results showed that DNMT3B was significantly negatively correlated with GRASP, HLA-DMB, HLA-DMA, CAB39, and TLE4, implying the predominant role of DNMT3B in periodontitis." (PMID 40267082, 2025).
pituitary adenomas (1 paper, 2017). "It was also shown that TLE2 and TLE4 were over-expressed in pituitary adenomas, and that TLE4 promoted cell proliferation and invasion, in part via activation of a JNK-c-Jun pathway, and subsequently increased cyclinD1 and decreased P27Kip1 expression." (PMID 27852056, 2017).
schwannoma (1 paper, 2024). A benign, usually encapsulated slow growing tumor composed of Schwann cells. "To elucidate if Sox10 expression is indeed regulated by Tle4 and Hes1, we used S16 Schwannoma cells and quantified the signal intensity of endogenous Sox10 immunofluorescence in these cells by flow cytometry after transfecting them with control plasmids or plasmids encoding Hes1, Tle4, or both." (PMID 38791273, 2024). "We found strong repression of U1 enhancer activity by Hes1 and of the U3 activity by Tle4 or Hes1 in Sox10-positive S16 Schwannoma cells." (PMID 38791273, 2024). "At least partially, this may be causative for the reduced Sox10 protein levels measured in Hes1/Tle4-transfected S16 Schwannoma cells." (PMID 38791273, 2024).
stomach adenocarcinoma (1 paper, 2025). "Pan-cancer analysis using the TCGA database revealed significant downregulation of TLE4 in multiple cancer types, including stomach adenocarcinoma (STAD)." (PMID 40406521, 2025).
thymoma (1 paper, 2022). A neoplasm arising from the epithelial cells of the thymus. "In contrast, levels of nuclear inhibitors were variably higher in thymomas and TCs than in NTs: TLE2 and TCF4 were significantly (p <0.01) higher in B3 thymomas and TCs, TLE4 only in B3 thymomas and TCF3 only in AB thymomas." (PMID 35965500, 2022).
cancer (12 papers, 2013 to 2025). A tumor composed of atypical neoplastic, often pleomorphic cells that invade other tissues. "TLE4 has been implicated in the regulation of various aspects of cancer progression and was found to be downregulated in GC based on TCGA data." (PMID 40406521, 2025). "Upregulation of SFRP2 and TLE4 suggests transcriptional inactivation of Wnt/β-catenin signaling, which leads to the suppression of cancer stemness and EMT40–42." (PMID 33270844, 2020). "The level of APH1A, CTBP1, HEY1, HEY2, JAG2, NOTCH4 was significantly higher in cancer samples compared to the control group, while the concentration of DTX1 TLE2, TLE4 was below the detection threshold." (PMID 41463075, 2025). "Interacting genes included well-established cancer-connected genes such as DNMT3A, SMAD2, MTCP1 and TLE4 (refs 36, 37, 38, 39)." (PMID 28534499, 2017). "We further focused on four key genes (CABYR, FOXF2, TLE4, and CDH1 ) related to proliferation, apoptosis, tumorigenesis, invasion and metastasis of cancer cells." (PMID 28121627, 2017). "Since the inhibitory effect of TLE4 on LEF1 has been previously established, this result further supports the role of miR-362-5p in inhibiting TLE4 expression, thereby promoting cancer progression." (PMID 40406521, 2025).
tumor (11 papers, 2016 to 2025). "In vivo tumorigenesis assay exhibited that knockdown of endogenous TLE4 expression in HCT116 cells caused significant inhibition of tumor growth (n = 5; P < 0.01)." (PMID 26701208, 2016). "Interestingly, TLE4 has previously been reported to have both a tumor suppressor function and to be associated with promoting tumor growth in different studies of different cancers." (PMID 33149219, 2020). "In acute myeloid lymphoma, loss of TLE1 or TLE4 increases cell proliferation suggesting that under some conditions TLE proteins may act as tumor suppressors." (PMID 30719233, 2019). "The list of potential tumor suppressor hits included both known factors, such as Ezh2 and Tle4, as well as novel candidates, including Kdm5c, Pcgf3, Chd1 and Pbrm1." (PMID 36631623, 2023). "In this study, TLE4 was shown to be able to promote proliferation, invasion and tumor growth in CRC, both in vitro and in vivo." (PMID 26701208, 2016). "The results showed that TLE4 protein located both in the cytoplasm (middle) and nucleus (right), and the expression of TLE4 increased markedly in 64% (86/134) CRC tumor tissue compared with that in adjacent non-tumor tissue." (PMID 26701208, 2016). "We next detected the effect of TLE4 overexpression on tumor growth using the nude mice xenograft model in vivo, using SW480-TLE4 and control cells." (PMID 26701208, 2016). "We found that TLE4 expression is significantly higher in CRC tissues than matched non-tumor mucosa tissues." (PMID 26701208, 2016). "In contrast, TLE4 overexpression in these cells inhibited tumor growth and metastasis." (PMID 39006072, 2024). "The specific gain of TLE4 and/or loss of ADAM3A loci and their association with tumor development, suggest important functions of these genes in the evolution of HEK293 cell lines, potentially through effects on proliferation and/or evasion of normal cell senescence of progeny cell lines." (PMID 33149219, 2020). "TLE1 and TLE4 were considered as tumor suppressors in hematological malignancy." (PMID 26701208, 2016). "On the contrary, knock down of TLE4 repressed cell proliferation, invasion and tumor growth." (PMID 26701208, 2016). "uncovered genes, including TLE4 and IKZF2, that are associated with T-cell exhaustion and effector function via screening of CAR-T cells, and identified genes, including RELA and NPLOC4, that are essential for tumor susceptibility to tumor killing via the reciprocal screening of GSCs." (PMID 35874698, 2022). "Moreover, TLE4 could promote cell proliferation and tumor growth invasion in CRC partially through acceleration of JNK/c-Jun pathway." (PMID 26701208, 2016). "Moreover, enforced expression of TLE4 in CRC cell lines significantly enhanced proliferation, invasion and tumor growth." (PMID 26701208, 2016). "Notably, TLE4 does not universally act as a tumor suppressor." (PMID 40406521, 2025).
TLE4 also shares sentences with these, for which no sentence is quoted: infection (8 papers); bacteremia (1); Blindness (1); bovine tuberculosis (1); breast carcinoma (1); deafness (1); epilepsy syndrome (1); gastric tumors (1); hepatoma (1); leukopenia (1); lymphopenia (1); papillary thyroid carcinoma (1); retinal ischemia (1); Usher syndrome type 1C (1); vitiligo (1).